LINC00293 (long independently transcribed non-coding RNA 293)
Synonyms: BEYLA; NCRNA00293
Gene: Long non-coding RNA gene on chromosome 8 (46,822,174 to 46,907,309, forward strand). Ensembl gene ENSG00000253314.
Diseases named in the same sentence as LINC00293 in open-access papers:
LINC00293 is named in the same sentence as 7 diseases in open-access papers, as found by Europe PMC text mining. Sharing a sentence is not in itself a finding about the gene and the disease. The quoted sentences say what the papers report.
breast carcinoma (1 paper, 2019). "In the presented study, we constructed and validated a 10‐lncRNA‐based signature (HAGLR, MIR210HG, RGMB‐AS1, TMEM161B‐AS1, CADM3‐AS1, LINC00293, LINC00910, LINC01187, PDZRN3‐AS1 and ZBED5‐AS1) to predict RFS for patients with breast cancer." (PMID 31429520, 2019).
LINC00293 also shares sentences with these, for which no sentence is quoted: Anxiety (1 paper); brain disorder (1); depression (1); hepatocellular carcinoma (1); lung carcinoma (1); thyroid papillary cancer (1).